CLTC (clathrin heavy chain)
Description:
Clathrin is the major protein of the polyhedral coat of coated pits and vesicles. Two different adapter protein complexes link the clathrin lattice either to the plasma membrane or to the trans-Golgi network. Acts as a component of the TACC3/ch-TOG/clathrin complex proposed to contribute to stabilization of kinetochore fibers of the mitotic spindle by acting as inter-microtubule bridge. The TACC3/ch-TOG/clathrin complex is required for the maintenance of kinetochore fiber tension. Plays a role in early autophagosome formation. Interaction with DNAJC6 mediates the recruitment of HSPA8 to the clathrin lattice and creates local destabilization of the lattice promoting uncoating (By similarity).
Synonyms: CLH-17; CLTCL2; Hc; CHC; CHC17; MRD56
Tractability: Small molecule: a structure with a bound ligand is known; it has a high-quality binding pocket. Antibody: UniProt places it where antibodies can reach, with high confidence; its Gene Ontology location is reachable by antibodies, with high confidence. PROTAC: ubiquitination databases record sites on it; its protein half-life has been measured; a small molecule that binds it is known.
Target class: Structural protein
Gene: Protein-coding gene on chromosome 17 (59,619,680 to 59,696,956, forward strand). Ensembl gene ENSG00000141367.
Subcellular location: Cytoplasmic vesicle membrane; Membrane, coated pit; Melanosome; Cytoplasm, cytoskeleton, spindle
Subcellular location (Human Protein Atlas): Endosomes; Lysosomes; Centriolar satellite; Cytosol; Mid piece; Mitotic spindle
Pathways (Reactome):
Vesicle-mediated transport: Cargo recognition for clathrin-mediated endocytosis; Clathrin-mediated endocytosis; Formation of annular gap junctions; Gap junction degradation; Golgi Associated Vesicle Biogenesis; Lysosome Vesicle Biogenesis
Signal Transduction: RHOU GTPase cycle; RHOV GTPase cycle; Retrograde neurotrophin signalling; WNT5A-dependent internalization of FZD2, FZD5 and ROR2; WNT5A-dependent internalization of FZD4
Disease: ALK mutants bind TKIs; Entry of Influenza Virion into Host Cell via Endocytosis; Signaling by ALK fusions and activated point mutants
Developmental Biology: EPH-ephrin mediated repulsion of cells; Recycling pathway of L1
Transport of small molecules: LDL clearance; VLDLR internalisation and degradation
Immune System: MHC class II antigen presentation
Gene Ontology:
Molecular function: clathrin light chain binding; disordered domain specific binding; double-stranded RNA binding; low-density lipoprotein particle receptor binding; protein binding; RNA binding; ubiquitin-specific protease binding; protein kinase binding; structural molecule activity
Biological process: amyloid-beta clearance by transcytosis; clathrin coat assembly; clathrin-dependent endocytosis; mitotic cell cycle; negative regulation of hyaluronan biosynthetic process; negative regulation of protein localization to plasma membrane; osteoblast differentiation; receptor internalization; receptor-mediated endocytosis; regulation of mitotic spindle organization; retrograde transport, endosome to Golgi; transferrin transport; chromosome segregation; clathrin coat disassembly; intracellular protein transport; mitotic spindle organization; vesicle-mediated transport
Cellular component: clathrin coat; clathrin complex; clathrin-coated vesicle; endosome; extracellular exosome; extracellular vesicle; focal adhesion; lysosome; membrane; mitotic spindle; mitotic spindle microtubule; protein-containing complex; spindle; clathrin-coated endocytic vesicle; clathrin-coated endocytic vesicle membrane; cytosol; endolysosome membrane; kinetochore microtubule; plasma membrane; trans-Golgi network membrane; clathrin coat of coated pit; clathrin coat of trans-Golgi network vesicle; clathrin-coated pit; cytoplasmic vesicle membrane; glutamatergic synapse; and 6 more
Genetic constraint (gnomAD): Loss-of-function variants: 11 observed, 174.51 expected, observed/expected ratio (o/e) 0.063, 90% interval 0.039 to 0.1. The upper end of that interval is the gene's LOEUF score, 0.1, which puts it in group 1 of 6, group 1 being the genes least tolerant of losing a copy. Missense variants: 742 observed, 1,992.1 expected, observed/expected ratio (o/e) 0.37, 90% interval 0.35 to 0.4. Synonymous variants: 628 observed, 685.09 expected, observed/expected ratio (o/e) 0.92, 90% interval 0.86 to 0.98.
Cancer hallmarks: genome instability and mutations (suppresses)
Homologues: Orthologues: chimpanzee CLTC (100% identical), guinea pig CLTC (100% identical), macaque CLTC (100% identical), dog CLTC (99% identical), rabbit CLTC (99% identical), rat Cltc (99% identical), mouse Cltc (99% identical), pig CLTC (99% identical), zebrafish cltcb (96% identical), tropical clawed frog cltc (95% identical), zebrafish cltca (95% identical), Drosophila melanogaster Chc (80% identical), and 1 more. Paralogues in human: CLTCL1 (83% identical), CLHC1 (8% identical).
Diseases named in the same sentence as CLTC in open-access papers:
CLTC is named in the same sentence as 70 diseases in open-access papers, as found by Europe PMC text mining. Sharing a sentence is not in itself a finding about the gene and the disease. The quoted sentences say what the papers report.
breast carcinoma (10 papers, 2013 to 2025). "miR-574-3p potentially targets clathrin heavy chain (CLTC) whose expression is associated with tamoxifen sensitivity in tamoxifen-resistant breast cancer cells." (PMID 26255816, 2015). "Clathrin heavy chain and cortactin have been reported to have their expression levels changed in breast cancer." (PMID 25948494, 2015). "CLTC immunoreactivity was predominantly detected in the cytoplasm of breast carcinoma cells, and it was also weakly observed in the epithelial cells of non-neoplastic glands adjacent to the carcinoma." (PMID 25560734, 2015). "Two datasets indicated that CLTC was substantially overexpressed in clinical breast cancers compared to normal breast tissues (by >2-fold; P < 0.001)." (PMID 25560734, 2015). "CLTC promoted tumorigenesis in hepatocellular carcinoma and cell growth in breast cancers." (PMID 34650983, 2021). "Additional 3ʹ VMP1 fusions in breast cancer include CLTC/VMP142 and AC099850.1/VMP143." (PMID 28983113, 2017). "When the positivity of CLTC was defined as stronger CLTC immunoreactivity in carcinoma cells versus their adjacent non-neoplastic epithelial cells, CLTC status was positive in 7 of 10 ER-positive breast carcinomas that we examined in the additional analysis (70%)." (PMID 25560734, 2015). "As in the present study we found that mRNA levels of CLTC were upregulated in OHTR cells and breast cancer tissues." (PMID 25560734, 2015). "RNA interference-mediated suppression of five candidate genes (DDX10, SKA3, EPHA5, CLTC and TNIK) led to inhibition of breast cancer cell growth." (PMID 23496902, 2013). "A recent study also identified the CLTC/VMP1 fusion in BT-549; our findings now demonstrate this to be a recurrent rearrangement in breast cancer." (PMID 23637631, 2013). "In this study, by integrating CRISPR-CAS9 functional genomics (DEPMAP database) and TCGA multi-omics data, seven key genes (CDK7, CLTC, COPB2, CRNKL1, GSPT1, NSF and PSMD12) that are closely related to the proliferation and prognosis of breast cancer were systematically identified." (PMID 40657358, 2025). "Based on the data, we assume that CLTC will be more involved in tamoxifen resistance in breast cancer cells rather than in estrogen sensitivity in naïve breast cancer cells." (PMID 25560734, 2015). "Using whole genome mate pair sequencing and RNA interference assays, we have discovered a number of novel gene rearrangements in breast cancer genomes and identified DDX10, SKA3, EPHA5, CLTC and TNIK as potential cancer genes with impact on the growth and proliferation of breast cancer cells." (PMID 23496902, 2013). "In addition, knockdown of CLTC using siRNA restored tamoxifen sensitivity in OHTR cells, and an examination of public microarray datasets revealed that low levels of CLTC expression correlated with better rates of survival for breast cancer patients." (PMID 25560734, 2015).
Intellectual disability (4 papers, 2022 to 2024). "Since the challenge, the CLTC variant has been reported as LP in ClinVar by an independent submitter in association with intellectual disability (ClinVar variation ID: 811,442)." (PMID 38685113, 2024). "De novo CLTC mutations underlie a spectrum of early-onset neurodevelopmental phenotypes having developmental delay/intellectual disability (ID), epilepsy, and movement disorders (MD) as major clinical features." (PMID 37324589, 2023). "Previous studies have shown that CLTC variants are linked to different phenotypes ranging from mild to severe intellectual disability, epilepsy, corpus callosum hypoplasia, and microcephaly." (PMID 36474209, 2022). "The third most poorly predicted diagnosis was a splice acceptor variant in CLTC (c.1534del, p.Val512LeufsTer11, ENST00000621829), a gene associated with intellectual disability in OMIM (MIM: 617,854)." (PMID 38685113, 2024). "Among genes with predicted probabilities greater than 0.90 (ranks 1–55), four genes (WDR45, CLTC, BRPF1, and GATAD2B) do not possess SFARI annotations, but have been associated with neurodegeneration and intellectual disability according to OMIM annotations." (PMID 35596027, 2023).
lung carcinoma (4 papers, 2010 to 2021). "Although normal lung tissue contains a mix of different cell types and not just the epithelial cells that give rise to NSCLC, this finding may imply the existence of a therapeutic window for CLTC inhibition in lung cancer." (PMID 32620799, 2020).
renal cell carcinoma (4 papers, 2010 to 2018). "Gene fusions involving clathrin heavy chain (CLTC) have been described in various leukemias (CLTC/ALK) and in renal cell carcinoma (CLTC/TFE3)." (PMID 23637631, 2013). "Teleologically, this anomaly may contribute to tumor development analogous to what has been suggested for CLTC fusions with ALK in inflammatory myofibroblastic tumors and anaplastic large-cell lymphomas, and with TFE3 in renal cell carcinomas." (PMID 21152103, 2010). "Interestingly, fusions of CLTC with the anaplastic lymphoma kinase (ALK) have been encountered in inflammatory myofibroblastic tumors and anaplastic large-cell lymphomas, whereas fusions with the transcription factor TFE3 have been encountered in renal cell carcinomas (RCC)." (PMID 21152103, 2010).
breast tumor (3 papers, 2007 to 2013). "Amplification and interchromosomal translocation of CLTC encoding the heavy chain of clathrin, which is required for the function of the mitotic spindle, were reported in two breast tumors." (PMID 23496902, 2013). "Finally, our data revealed seven other protein coding genes (FAM33A, DHX40, CLTC, PTRH2, TMEM49, TUBD1, ABC1, and USP32) that have not been implicated previously in 17q23 studies, but whose expression was clearly associated with copy number status in primary breast tumours." (PMID 17353917, 2007).
colon cancer (3 papers, 2013 to 2022). "Inhibition of CLTC was previously shown to induce apoptosis in colon cancer cell lines by disrupting bipolar spindle formation." (PMID 32620799, 2020).
Huntington disease (3 papers, 2009 to 2014). Huntington disease (HD) is a rare neurodegenerative disorder of the central nervous system characterized by unwanted choreatic movements, behavioral and psychiatric disturbances and dementia. "In the Huntington's disease, parkingson's disease, oxidative phosphorylation, and alzheimer's disease pathways, CLTC is involved in inflammatory myofibroblastic tumors and lower expression of MAPT is associated with HER2 overexpression." (PMID 23369492, 2013). "These include genes in the pathways for amyotrophic lateral sclerosis (NEF3, NEFL, NEFH), Huntington's disease (CALM3, CLTC, CLTB), neurodegenerative disorders (APLP1, NEFH, FBXW7), Parkinson's disease (GPR37) and prion disease (APLP1, NFE2L2)." (PMID 19948073, 2009).
osteosarcoma (3 papers, 2021 to 2024). A usually aggressive malignant bone-forming mesenchymal neoplasm, predominantly affecting adolescents and young adults. "As these two signaling pathways are suggested to have a pro‐tumorigenic effect in osteosarcoma, our results partly explain the molecular mechanism underlying the pro‐tumor effect of CLTC." (PMID 34185412, 2021). "High CLTC expression is associated with worse clinical outcomes in osteosarcoma patients." (PMID 34185412, 2021). "For example, CLTC facilitates the oncogenesis and progression in osteosarcoma by activating the TGF-beta and AKT/mTOR signaling pathways." (PMID 39850878, 2024). "The high expression of CLTC has also been shown to be an independent prognostic factor for tumor-free survival and overall survival in patients with osteosarcoma." (PMID 35686089, 2022). "Further studies confirmed that SP1 binds to the CLTC promoter at the −320 to −314‐nt and +167 to +173‐nt loci and promotes the transcriptional activity of CLTC in osteosarcoma." (PMID 34185412, 2021). "This promising new datum prompted us to analyze the potential mechanism for CLTC deregulation in osteosarcoma." (PMID 34185412, 2021). "The IHC results (H score) indicated that CLTC expression was significantly higher in the osteosarcoma tissues than in the matched normal tissues." (PMID 34185412, 2021). "In this study, we identified that SP1 binds to the CLTC promoter at the −320 to −314‐nt and +167 to +173‐nt loci and activates CLTC expression in osteosarcoma cells." (PMID 34185412, 2021). "In conclusion, our study provides mechanistic insights into the oncogenic effect of CLTC, and understanding of the SP1/CLTC/TFG axis serves a novel therapeutic strategy for patients with osteosarcoma." (PMID 34185412, 2021). "To investigate the correlation between TFG and CLTC in clinical samples, we used osteosarcoma TMA to demonstrate their relationship." (PMID 34185412, 2021). "Taken together, CLTC knockdown had a tumor‐suppressive effect in osteosarcoma both in vitro and in vivo." (PMID 34185412, 2021). "The colony formation assay demonstrated that down‐regulation of CLTC attenuated the ability of osteosarcoma cells to form colonies." (PMID 34185412, 2021). "Down‐regulation of CLTC inhibited cell proliferation, promoted apoptosis, and blocked the cell cycle transition in osteosarcoma." (PMID 34185412, 2021). "To better understand the role of TFG in CLTC‐mediated osteosarcoma progression, we first investigated the function of TFG." (PMID 34185412, 2021). "In conclusion, this study demonstrated that the expression of CLTC was an independent prognostic factor for patients with osteosarcoma." (PMID 34185412, 2021). "High expression of CLTC was found to be an independent prognostic factor for tumor‐free survival and overall survival of patients with osteosarcoma." (PMID 34185412, 2021). "Collectively, these findings suggested that CLTC is highly expressed in osteosarcoma and is a valuable prognostic factor for patients with osteosarcoma." (PMID 34185412, 2021). "Based on the combinatorial analysis of bioinformatics and functional screening, clathrin heavy chain (CLTC) was selected and confirmed as a new biomarker and potential therapeutic target for patients with osteosarcoma." (PMID 34185412, 2021). "The results showed that CLTC knockdown significantly decreased the half‐life of TFG in the osteosarcoma cells." (PMID 34185412, 2021). "In line with our findings, these results also supported that the apoptosis of osteosarcoma cells was affected by the expression of CLTC." (PMID 34185412, 2021). "Although the intrinsic mechanisms leading to abnormal gene expression are very complex, our findings partly account for the high expression of CLTC in osteosarcoma." (PMID 34185412, 2021). "In conclusion, these results confirmed that CLTC interacts with TFG in osteosarcoma cells and promotes the protein stabilization of TFG." (PMID 34185412, 2021).
osteosarcoma (continued). "SP1 knockdown osteosarcoma cells showed lower mRNA and protein levels of CLTC than that in the control cells in our study." (PMID 34185412, 2021). "Thus, inhibition of CLTC or its interaction with TFG provides a valuable approach for developing effective pharmacological strategies for the treatment of osteosarcoma." (PMID 34185412, 2021). "In this study, CLTC was selected and considered as a therapeutic target in osteosarcoma." (PMID 34185412, 2021). "Herein, we identified TFG as an interacting protein of CLTC and as an oncogene in osteosarcoma." (PMID 34185412, 2021). "Thus, we first revealed the linkage between transcription factor SP1 and CLTC expression in osteosarcoma." (PMID 34185412, 2021). "Inhibition of CLTC suppresses osteosarcoma growth both in vitro and in vivo." (PMID 34185412, 2021). "In this study, we found that high expression of clathrin heavy chain (CLTC) was an independent prognostic factor for tumor‐free survival (HzR, 3.049; 95% CI, 1.476–6.301) and overall survival (HzR, 2.469; 95% CI, 1.005–6.067) of patients with osteosarcoma." (PMID 34185412, 2021). "However, the biological function and molecular mechanism of CLTC in osteosarcoma remain unexplored." (PMID 34185412, 2021). "Moreover, we observed that CLTC knockdown promoted apoptosis in the osteosarcoma cells." (PMID 34185412, 2021). "Moreover, WB also confirmed that CLTC knockdown could inhibit the activation of AKT/mTOR signaling in osteosarcoma." (PMID 34185412, 2021). "As pro‐tumorigenic TGF‐β and AKT/mTOR signaling pathways were driven by CLTC in osteosarcoma, our study also encourages the development of TGF‐β inhibitors and AKT inhibitors for osteosarcoma therapy." (PMID 34185412, 2021). "We detected and compared CLTC expression via IHC analysis in osteosarcoma TMA, which contained 102 pairs of matched osteosarcoma and normal tissues." (PMID 34185412, 2021). "Meanwhile, the immunofluorescence (IF) assay showed positive co‐localization between CLTC and TFG in the osteosarcoma cells." (PMID 34185412, 2021). "Therefore, SP1 may regulate the expression of CLTC and mediate the proliferation of osteosarcoma." (PMID 34185412, 2021). "However, how CLTC plays a pro‐tumor function in osteosarcoma remains unclear." (PMID 34185412, 2021). "Considering that TFG is a downstream protein of CLTC and has an oncogenic effect, we next hypothesized that CLTC functions in a TFG‐dependent manner in osteosarcoma." (PMID 34185412, 2021). "Moreover, both CLTC and SEPT11 were found to have consistently high expression in all osteosarcoma cells when compared to those in the osteoblast cells; conversely, the other two genes (GALNT1 and TMEM2) were not." (PMID 34185412, 2021). "The consistently high expression of CLTC and SEPT11 indicated that they might contribute to the tumorigenesis of osteosarcoma." (PMID 34185412, 2021). "The deregulation of CLTC and TFG is emerging as a unique target for osteosarcoma." (PMID 34185412, 2021). "Meanwhile, down‐regulation of both CLTC and TFG was found to activate ER stress in osteosarcoma." (PMID 34185412, 2021). "In addition, CLTC and TFG can be used as postoperative pathological indicators to predict the prognosis of patients with osteosarcoma." (PMID 34185412, 2021). "The role of CLTC in osteosarcoma has also not been explored." (PMID 34185412, 2021). "However, the migration ability of the osteosarcoma cells was not affected by the expression of CLTC." (PMID 34185412, 2021).